SIGLEC1 (sialic acid binding Ig like lectin 1)
Description:
Macrophage-restricted adhesion molecule that mediates sialic-acid dependent binding to lymphocytes, including granulocytes, monocytes, natural killer cells, B-cells and CD8 T-cells. Plays a crucial role in limiting bacterial dissemination by engaging sialylated bacteria to promote effective phagocytosis and antigen presentation for the adaptive immune response. Mediates the uptake of various enveloped viruses via sialic acid recognition and subsequently induces the formation of intracellular compartments filled with virions (VCCs). In turn, enhances macrophage-to-T-cell transmission of several viruses including HIV-1 or SARS-CoV-2. Acts as an endocytic receptor mediating clathrin dependent endocytosis. Preferentially binds to alpha-2,3-linked sialic acid. Binds to SPN/CD43 on T-cells (By similarity). May play a role in hemopoiesis. Plays a role in the inhibition of antiviral innate immune by promoting TBK1 degradation via TYROBP and TRIM27-mediated ubiquitination. (Microbial infection) Facilitates viral cytoplasmic entry into activated dendritic cells via recognition of sialylated gangliosides pesent on viral membrane.
Synonyms: Siglec-1; CD169; SN; FLJ00051; FLJ00055; FLJ00073; FLJ32150; dJ1009E24.1
Tractability: Antibody: UniProt places it where antibodies can reach, with high confidence; its Gene Ontology location is reachable by antibodies, with high confidence; UniProt predicts a signal peptide or a membrane-spanning region.
Gene: Protein-coding gene on chromosome 20 (3,686,970 to 3,712,647, reverse strand). Ensembl gene ENSG00000088827.
Subcellular location: Cell membrane (Isoform 1); Secreted (Isoform 2)
Pathways (Reactome):
Immune System: Immunoregulatory interactions between a Lymphoid and a non-Lymphoid cell
Gene Ontology:
Molecular function: carbohydrate binding; virion binding
Biological process: negative regulation of type I interferon production; cell-cell adhesion; cell-matrix adhesion; clathrin-dependent endocytosis of virus by host cell; inflammatory response
Cellular component: plasma membrane; early endosome; late endosome; membrane; extracellular region
Genetic constraint (gnomAD): Loss-of-function variants: 132 observed, 142.51 expected, observed/expected ratio (o/e) 0.93, 90% interval 0.8 to 1.07. The upper end of that interval is the gene's LOEUF score, 1.07, which puts it in group 4 of 6, group 1 being the genes least tolerant of losing a copy. Missense variants: 2,253 observed, 2,284.2 expected, observed/expected ratio (o/e) 0.99, 90% interval 0.95 to 1.02. Synonymous variants: 945 observed, 975.41 expected, observed/expected ratio (o/e) 0.97, 90% interval 0.92 to 1.02.
Homologues: Orthologues: chimpanzee SIGLEC1 (99% identical), macaque SIGLEC1 (95% identical), pig SIGLEC1 (78% identical), dog SIGLEC1 (77% identical), rabbit SIGLEC1 (77% identical), guinea pig SIGLEC1 (74% identical), mouse Siglec1 (73% identical), rat Siglec1 (72% identical), tropical clawed frog siglec1 (35% identical). Paralogues in human: SIGLEC5 (9% identical), SIGLEC10 (8% identical), SIGLEC11 (8% identical), MAG (7% identical), SIGLEC8 (7% identical), SIGLEC7 (7% identical), SIGLEC12 (7% identical), SIGLEC9 (6% identical), SIGLEC6 (6% identical), TMEM25 (6% identical), SIGLEC14 (6% identical), CD33 (6% identical), and 4 more.
Diseases named in the same sentence as SIGLEC1 in open-access papers:
SIGLEC1 is named in the same sentence as 165 diseases in open-access papers, as found by Europe PMC text mining. Sharing a sentence is not in itself a finding about the gene and the disease. The quoted sentences say what the papers report.
COVID-19 (49 papers, 2021 to 2026). A disease caused by infection with severe acute respiratory syndrome coronavirus 2. "SIGLEC1 (encoding CD169) transcript was mainly detected within clusters of monocytes and appeared to be increased in a few COVID-19 patients." (PMID 34394090, 2021). "Although CD169/SIGLEC1 is suggested to have an additional diagnostic value in COVID-19, it remains unclear whether expression levels represent a bystander or a direct contributor to the pathogenesis of COVID-19." (PMID 33825125, 2021). "Independent investigations have also found that genes related with some of these transcripts (IGI27, SEMA4D, SIGLEC1, and SERPINA1) are repressed in severe COVID-19, underlining their potential as early predictors of severity." (PMID 37918965, 2024). "SIGLEC6 belongs to the family of sialic acid-binding immunoglobulin-like lectin proteins, out of which SIGLEC1, SIGLEC7 and SIGLEC10 have been implicated to play a role in COVID-19." (PMID 35438176, 2022). "The early phases of COVID-19 were characterized by an enrichment of CD169/Siglec1+ monocytes in the peripheral blood." (PMID 35326463, 2022). "To analyze for possible associations between CD169/SIGLEC1 expression levels and disease severity of COVID-19, we performed Pearson correlations." (PMID 33825125, 2021). "In agreement, CD169/SIGLEC1 expression has been proposed as a marker in the diagnosis of early COVID-19." (PMID 33825125, 2021). "In this retrospective observational study, CD169/SIGLEC1 expression was upregulated on circulating monocytes of COVID-19 patients with mild disease." (PMID 33825125, 2021). "Within this range, 0–9 days after onset of symptoms, patients with mild COVID-19 showed an increased CD169/SIGLEC1 expression compared to patients with severe COVID-19, and also compared to SARS-CoV-2 negative patients (p < 0.0001 for both comparisons)." (PMID 33825125, 2021). "Our analysis showed an increase in SIGLEC1 in CD16+ monocytes from COVID-19 cases compared to healthy cases, as well as when comparing mild cases to healthy controls." (PMID 34108966, 2021). "Focusing on monocytes, we observed that SIGLEC1 was highly increased in cluster 22, which was a cluster almost exclusively comprised of COVID-19 patients." (PMID 34394090, 2021). "As an example, the sialic acid binding Ig like lectin 1 (SIGLEC1/CD168) protein, which is found on circulating monocytes in COVID-19 and expression levels are associated with disease severity." (PMID 34844191, 2021). "Another flow cytometry study reported increased CD169/SIGLEC1 protein expression on total monocytes from COVID-19 cases with mild disease compared to those with severe disease." (PMID 34108966, 2021). "In our transcriptomic data we identified increased SIGLEC1 gene expression in COVID-19." (PMID 36522333, 2022). "In contrast, patients with severe COVID-19 showed almost normal expression levels of CD169/SIGLEC1." (PMID 33825125, 2021). "Of the five proteins differentially expressed in cMs, four [transferrin receptor (TFRC), sialic acid binding Ig-like lectin 1 (SIGLEC1), Fc fragment of IgG receptor 1a (FCGR1A), and leukocyte-associated Ig-like receptor 1 (LAIR1)] were higher expressed in COVID-19+ cases." (PMID 34429372, 2021). "Taken together, the larger effect size between COVID-19 and healthy controls as well as the higher expression levels in monocytes suggested that IFI27 and SIGLEC1 is a monocyte-specific biomarker with slightly different property in response to viral infection." (PMID 38268924, 2023). "Recent studies found low CD169/Siglec1 and high CD163 expression on circulating monocytes in severe COVID-19 patients." (PMID 35326463, 2022). "A single cell study showed increased SIGLEC1 and VCAN in CD14+ monocytes from COVID-19 donors compared to healthy controls." (PMID 34108966, 2021). "Among patients with mild COVID-19, there was a time-dependent expression of CD169/SIGLEC1 with the highest values within the first 3 days after onset of symptoms." (PMID 33825125, 2021).
COVID-19 (continued). "Since in COVID-19, the median duration from onset of symptoms to ARDS is 9 days, we first compared CD169/SIGLEC1 expression levels in this early phase of infection." (PMID 33825125, 2021). "We observed SIGLEC1 expression increased at greater intensity as early as day 0-3 post infection in severe/critical versus mild/moderate patients, suggesting stronger and a more immediate type I IFN response in severe COVID-19." (PMID 36522333, 2022). "SIGLEC1 (CD169) is an IFN-inducible gene that acts as an endocytic receptor mediating clathrin-dependent endocytosis and has been reported to be upregulated in circulating monocytes in COVID-19 patients." (PMID 35115549, 2022). "In line with the literature that CD169/SIGLEC1 expression is not specific for COVID-19, three out of 27 COVID-19 screening patients tested negative for SARS-CoV-2 showed CD169/SIGLEC1 expression levels above the normal range." (PMID 33825125, 2021). "Here, we analyzed expression of CD169/SIGLEC1, a well described downstream molecule in interferon signaling, and found increased monocytic CD169/SIGLEC1 expression levels in patients with mild, acute COVID-19, compared to patients with severe disease." (PMID 33825125, 2021). "We recommend further clinical studies to evaluate the value of CD169/SIGLEC1 expression in patients with COVID-19 with or without auto-antibodies against type I interferons." (PMID 33825125, 2021). "Additionally, it is worth noting that the gene SIGLEC1 is apparently specific to monocytes in both COVID-19 and normal samples." (PMID 38268924, 2023). "In contrast, CD169/SIGLEC1 expression in most COVID-19 patients with severe disease ranged in almost normal levels comparable with screening patients following exclusion of COVID-19, although control patients were not matched in regard to sex." (PMID 33825125, 2021). "Interestingly, CD169/SIGLEC1 levels in patients with severe COVID-19 were similar to SARS-CoV-2 negative patients." (PMID 33825125, 2021). "The intermediate monocytes (consistently present in COVID-19) were characterized by a pronounced antiviral, interferon-driven response, as illustrated by the upregulation of both interferon-inducible and stimulated genes (IFI6, IFI27, IFI44L, and ISG15, SIGLEC1)." (PMID 34424199, 2021).
viral infection (48 papers, 2013 to 2025). "Numerous preclinical studies have demonstrated the protective role of sialoadhesin or siglec-1 (CD169) expressed on the MO membrane in viral infections." (PMID 39519183, 2024). "To determine the specificity of SIGLEC1-mediated binding to the ganglioside to promote the virus infection, we overexpressed the wild-type SIGLEC1 or R116A mutant in HeLa cells, and infected with SARS-CoV-2, HCoV-229E, or HCoV-OC43." (PMID 36726758, 2023). "While the ACE2 overexpression conferred the cells to be permissive and over 50% of cells were positive for N protein, the expression of SIGLEC1 promoted the virus infection to around 25%." (PMID 36726758, 2023). "SIGLEC1 is also involved in the immune response to viral infection and is upregulated following the detection of type 1 interferons." (PMID 36873940, 2023). "SIGLEC1 has been reported to be up-regulated upon viral infection through the IFN/JAK/STAT1 signaling pathway, which spreads the infection and helps virus to escape from neutralization." (PMID 35470857, 2022). "Siglec1 promotes viral infection and phagocytosis by mediating the combination of pathogens and macrophages." (PMID 36389805, 2022). "We and others have previously shown that CD169/Siglec-1 facilitates viral infections of macrophages or dendritic cell (DC)-mediated trans infection of bystander cells." (PMID 36279285, 2022). "Previous studies have demonstrated an important role of CD169/SIGLEC-1 in different viral infections, including those from Ebola virus and human immunodeficiency virus (HIV)." (PMID 34959594, 2021). "Previous studies have demonstrated an important role of CD169/SIGLEC1 in different other viral infections, including Ebola virus and human immunodeficiency virus (HIV)." (PMID 33825125, 2021). "In some cell types such as HeLa, other known or unknown candidate receptors instead of ACE2 may coordinate with SIGLEC1 to enhance the virus infection." (PMID 36726758, 2023). "Moreover, to assess if SIGLEC1 facilitating virus infection is mediated by the primary receptor ACE2, three ACE2-deficient cell lines, HeLa, A549, and 293T, were employed." (PMID 36726758, 2023). "In addition, SIGLEC1, an immunoregulatory marker in viral infections, was more highly expressed in primigravid women." (PMID 37634385, 2023). "Further study of the effect of increased SIGLEC-1 expression on the observed viral infections in DADA2 may shed light on the intriguing coalescence of the type I IFN signature and susceptibility to viral infection." (PMID 34657246, 2021). "The functionality of Siglec‐1 during viral infection differs between viruses." (PMID 29266251, 2018). "Since expression of SIGLEC1 is present on AMs, and blockade of SIGLEC1 ex vivo significantly reduced the SARS-CoV-2 infection, it would be intriguing to investigate if SIGLEC1 could promote virus infection in vivo, especially in the lung where AMs are abundant." (PMID 36726758, 2023). "Thus, blockade of the SIGLEC1 could potentially reduce the virus infection in the lung where the AMs are abundant." (PMID 36726758, 2023). "Therefore, macrophages expressing Siglec1 can exert phagocytosis to facilitate viral infection." (PMID 36389805, 2022). "Research has identified several leukocyte activation markers that hold promise for diagnosing and distinguishing bacterial and viral infections: particularly the expression of CD64 (FcgRI) on neutrophils (nCD64) and CD169 (Siglec-1) on classical monocytes (mCD169) (7, –, 11)." (PMID 41159746, 2025). "Interestingly, recent works have identified sialoadhesin CD169 (Sn or SIGLEC‐1), a member of the sialic acid‐binding immunoglobulin‐like lectins (SIGLEC) family, as having a role during viral infections." (PMID 32031762, 2020).
melanoma (18 papers, 2016 to 2025). A malignant, usually aggressive tumor composed of atypical, neoplastic melanocytes. "The mutation frequency of SIGLEC7 is up to 8% in melanoma, whereas those of SIGLEC1 and CD22 are up to 7%." (PMID 37207210, 2023). "Studies also showed that macrophages expressing SIGLEC1 in the subcapsular sinus provide the correct environment for melanoma lymph node metastasis." (PMID 37207210, 2023). "Siglec1-positive subcapsular sinus macrophages have been reported to provide a “soil” for LNM of melanoma cells." (PMID 35844788, 2022). "However, other studies have shown that SIGLEC1 can inhibit tumor growth, and SIGLEC1-positive macrophages inhibit melanoma by limiting tumor-derived vesicle-B cell interaction." (PMID 37207210, 2023).
breast carcinoma (17 papers, 2016 to 2025). "Finally, a SIGLEC-1+TAM is described in human breast cancer associated with aggressive subtypes and shorter survival; however, their developmental origin remains transcriptionally unique." (PMID 39104525, 2024). "In breast cancer, CD169 also marked tumor-associated macrophages and SIGLEC1 expression was associated with poor outcome." (PMID 34394090, 2021). "We used multicolor flow cytometric analysis to determine SIGLEC1 expression at the protein level in an independent cohort of breast cancer patients and found that SIGLEC1 was expressed on Br-TAM, but not on other immune cells or CD45− non-immune cells, indicating specificity to macrophages/TAMs." (PMID 30930117, 2019). "identify a breast cancer tumor-associated macrophage (TAM) transcriptome that is different from those of monocytes and tissue-resident macrophages, and which is associated with shorter disease-specific survival, and they demonstrate crosstalk between tumor cells and TAMs via SIGLEC1, CCL8, and CSF1." (PMID 30930117, 2019). "Breast cancer TAMs express CCL8, which is chemotactic for monocytes and drives a positive regulatory loop between cancer cells and TAMs through CSF1 and TNF-α, which upregulates SIGLEC1." (PMID 30930117, 2019).
autoimmune disease (13 papers, 2015 to 2025). A disorder resulting from loss of function or tissue destruction of an organ or multiple organs, arising from humoral or cellular immune responses of the individual to their own tissue constituents. "It has been reported that SIGLEC1 is abnormally expressed in various autoimmune diseases and can serve as a potential clinical marker, such as monogenic interferonopathies, systemic lupus erythematosu, autoimmune congenital heart block, and primary Sjögren’s syndrome." (PMID 36544770, 2022).
HIV-1 infection (12 papers, 2007 to 2024). The type species of lentivirus and the etiologic agent of acquired immunodeficiency syndrome (AIDS). "The identification of two homozygous HIV-1-infected individuals with a confirmed loss-of-function variant in SIGLEC1, both of whom were infected via mucosal exposure, indicates that Siglec-1 trans-infection is not indispensable to establish HIV-1 infection through sexual contact." (PMID 27510803, 2016). "The receptor Siglec-1 (CD169) potently enhances HIV-1 trans-infection and is regulated by immune activating signals present throughout the course of HIV-1 infection, such as interferon α (IFNα)." (PMID 25947229, 2015).
colorectal cancer (11 papers, 2015 to 2025). A primary or metastatic malignant neoplasm that affects the colon or rectum. "Infiltration of SIGLEC1+ macrophages in colorectal cancer was associated with tumor progression, but in hepatocellular carcinoma they predicted favorable patient outcomes, underpinning the hypothesis that TAM phenotypes/activation are organ and cancer specific." (PMID 30930117, 2019). "We studied the prognostic value of SIGLEC1 in colorectal cancer (CRC) using bioinformatics." (PMID 39744582, 2025). "Among them, MMP12 was highly expressed in colorectal cancer tissues, while ARMCX2, CEBPA, CXCL13, FABP4, HOXC6, SIGLEC1 and VSIG4 were more expressed in normal tissues than in cancer tissues." (PMID 36544770, 2022).
hepatocellular carcinoma (11 papers, 2015 to 2026). A malignant tumor that arises from hepatocytes. "Consistent with our findings, SIGLEC1+ macrophages have been identified in colorectal and hepatocellular carcinoma." (PMID 30930117, 2019).
systemic lupus erythematosus (11 papers, 2011 to 2025). An autoimmune multi-organ disease typically associated with vasculopathy and autoantibody production. "In this prospective study, we aimed to investigate the association of serum (s) and urine (u) IP-10, galectin-9, and SIGLEC-1 with disease activity in patients with systemic lupus erythematosus (SLE)." (PMID 39050398, 2024).
glioma (9 papers, 2020 to 2025). A benign or malignant brain and spinal cord tumor that arises from glial cells (astrocytes, oligodendrocytes, ependymal cells). "FPR3 and SIGLEC1 were high expression genes in glioma associated with grades and IDH status." (PMID 33408717, 2020). "A large sample survey is needed to identify the expression of SIGLEC1 in glioma." (PMID 33408717, 2020). "To determine if CD169+ macrophage infiltration affected patient survival, we analyzed the CD169 expression (SIGLEC1) and overall survival of human glioma patients in The Cancer Genome Atlas (TCGA) database." (PMID 36266311, 2022). "Meanwhile we explored the role of SIGLEC1 (also known as CD169) and FPR3 in the prognosis and immunotherapy of glioma and thought them would be new biomarkers and targets in diagnoses and treatment of glioma." (PMID 33408717, 2020). "However, the role of FPR3 and SIGLEC1 in glioma still not be explored." (PMID 33408717, 2020).